BLTP3A (bridge-like lipid transfer protein family member 3A)
Description:
Tube-forming lipid transport protein which probably mediates the transfer of lipids between membranes at organelle contact sites. May be involved in the retrograde traffic of vesicle clusters in the endocytic pathway to the Golgi complex.
Synonyms: C6orf107; UHRF1BP1; FLJ20302; dJ349A12.1; ICBP90; SHIP164B
Tractability: PROTAC: ubiquitination databases record sites on it.
Gene: Protein-coding gene on chromosome 6 (34,792,083 to 34,877,514, forward strand). Ensembl gene ENSG00000065060.
Subcellular location: Late endosome
Subcellular location (Human Protein Atlas): Nuclear membrane; Nucleoplasm; Cytosol
Gene Ontology:
Molecular function: histone deacetylase binding; identical protein binding; protein binding
Cellular component: late endosome
Genetic constraint (gnomAD): Loss-of-function variants: 85 observed, 149.94 expected, observed/expected ratio (o/e) 0.57, 90% interval 0.47 to 0.68. The upper end of that interval is the gene's LOEUF score, 0.68, which puts it in group 2 of 6, group 1 being the genes least tolerant of losing a copy. Missense variants: 1,540 observed, 1,840.7 expected, observed/expected ratio (o/e) 0.84, 90% interval 0.8 to 0.87. Synonymous variants: 585 observed, 683.02 expected, observed/expected ratio (o/e) 0.86, 90% interval 0.8 to 0.92.
Homologues: Orthologues: chimpanzee BLTP3A (99% identical), macaque BLTP3A (98% identical), dog BLTP3A (91% identical), rabbit BLTP3A (90% identical), pig BLTP3A (87% identical), rat Bltp3a (84% identical), mouse Bltp3a (83% identical), guinea pig BLTP3A (70% identical), zebrafish bltp3a (44% identical), tropical clawed frog bltp3a (35% identical), Drosophila melanogaster CG34126 (27% identical), Caenorhabditis elegans C44H4.4 (18% identical). Paralogues in human: BLTP3B (41% identical).
Diseases named in the same sentence as BLTP3A in open-access papers:
BLTP3A is named in the same sentence as 16 diseases in open-access papers, as found by Europe PMC text mining. Sharing a sentence is not in itself a finding about the gene and the disease. The quoted sentences say what the papers report.
systemic lupus erythematosus (7 papers, 2017 to 2025). An autoimmune multi-organ disease typically associated with vasculopathy and autoantibody production. "As lysosomes play a key role in cells of the immune system, it is of special interest that several coding variants of BLTP3A are associated with susceptibility to systemic lupus erythematosus (SLE), a chronic autoimmune disease." (PMID 39386594, 2025). "Mutations in BLTP3A by contrast are found as a susceptibility locus for systemic lupus erythematosus (SLE), a debilitating autoimmune condition where episodes are often triggered by exposure to UV light." (PMID 40356703, 2025).
BLTP3A also shares sentences with these, for which no sentence is quoted: lung adenocarcinoma (3 papers); Allergy (1); Alzheimer disease (1); bladder cancer (1); cancer (1); cervical cancer (1); colon cancer (1); COVID-19 (1); Down syndrome (1); Huntington disease (1); mental retardation (1); neurodevelopmental disorder (1); Obesity (1); Tics (1); tumor (1).